VCX2 (variable charge X-linked 2)
Description:
May mediate a process in spermatogenesis or may play a role in sex ratio distortion.
Synonyms: VCX-2r; VCX2R; VCXB
Tractability: No criterion of Open Targets' tractability assessment is met for any kind of drug.
Gene: Protein-coding gene on chromosome X (8,169,944 to 8,171,267, reverse strand). Ensembl gene ENSG00000177504.
Gene Ontology:
Biological process: brain development
Homologues: Paralogues in human: VCX (88% identical), VCX3A (88% identical), VCX3B (88% identical), VCY (76% identical), VCY1B (76% identical).
Diseases named in the same sentence as VCX2 in open-access papers:
VCX2 is named in the same sentence as 10 diseases in open-access papers, as found by Europe PMC text mining. Sharing a sentence is not in itself a finding about the gene and the disease. The quoted sentences say what the papers report.
bladder cancer (1 paper, 2020). "Again, VCX2 was much less frequently expressed in cancers compared to GAGE and MAGE-A CT antigens, which we previously detected in 10-40% of tumors of multiple cancer types (e.g., melanoma, lung cancer, bladder cancer, and breast cancer)." (PMID 33634013, 2020).
breast carcinoma (1 paper, 2020). "We then investigated VCX2 protein expression in a large panel of cell lines from breast cancer and melanoma." (PMID 33634013, 2020). "VCX2 was expressed in only 2/103 primary melanomas and 4/368 metastatic melanomas, and only expressed at a very low level in a subset of breast cancers." (PMID 33634013, 2020). "The VCX2 protein was expressed in only 1/11 breast cancer cell lines (i.e., T-47-D) and in 4/19 melanoma cell lines (i.e., FM45, FM79, A375, and Sk-Mel-37b) and three of the cell lines showed a very low number (<5%) of VCX2 positive cells (i.e., FM79, A375, and Sk-Mel-37b)." (PMID 33634013, 2020). "VCX2 protein expression was investigated in multiple cancer types, but the focus was mostly on melanoma, as CT antigen expression tends to be high in this cancer type, and breast cancer, where new immunogenic targets are much needed." (PMID 33634013, 2020). "RNA sequencing analysis also indicated that VCX2 might be less frequently expressed in melanoma and breast cancer than other VCX gene family members (VCX and VCX3A)." (PMID 33634013, 2020). "A similar pattern was seen with the hormone receptor positive breast cancer cells MCF7; guadecitabine increased the frequency of VCX2-positive cells (from 0 to 23%) and again this was potentiated by addition of valproic acid (42%)." (PMID 33634013, 2020). "Indeed, treatment of breast cancer and melanoma cell lines with the DNA methyltransferase inhibitor guadecitabine, alone or in combination with histone deacetylase (HDAC) inhibitor valproic acid, promoted loss of VCX2 promoter DNA methylation and induced VCX2 expression." (PMID 33634013, 2020). "We found that the expression level of VCX2 and other VCX genes correlate with promoter methylation in breast cancer and melanoma, suggesting that these genes can be induced by DNA methyltransferase inhibitors." (PMID 33634013, 2020). "With the potential of clarifying if the VCX/Y family genes could be induced by demethylation, we investigated if the expression of VCX2 and other VCX genes were correlated with promoter methylation in breast cancer and melanoma." (PMID 33634013, 2020). "Importantly, we found that expression of VCX2 was inversely correlated with promoter methylation and could be activated by treatment with a DNA methyltransferase inhibitor in multiple breast cancer and melanoma cell lines and a breast cancer patient-derived xenograft." (PMID 33634013, 2020).
melanoma (1 paper, 2020). A malignant, usually aggressive tumor composed of atypical, neoplastic melanocytes. "Our analysis of VCX2 expression demonstrated that VCX2 was predominantly located in the nuclei of cells in both testis germ cells and melanoma." (PMID 33634013, 2020). "Among malignancies, VCX2 was only found in tumors of a small subset of melanoma patients and thus rarely expressed compared to other cancer/testis antigens such as GAGE and MAGE-A." (PMID 33634013, 2020). "Using western blotting we confirmed that the antibody indeed recognized a band corresponding to VCX2 in melanoma cells." (PMID 33634013, 2020). "This supported the result of our immunohistochemical analysis of VCX2 expression and further indicated that this CT antigen is a potential target in only a small subset of melanomas." (PMID 33634013, 2020). "To investigate if VCX2 exhibited a similar nuclear distribution in cancer cells, we performed a detailed analysis of its nuclear localization in A375 melanoma cells using fluorescence microscopy." (PMID 33634013, 2020). "Our results suggest that VCX2 may be a target for immunotherapy in only a small subset of melanoma patients." (PMID 33634013, 2020). "This suggested that VCX2 is only a useful target for treatment of a subset of melanoma patients." (PMID 33634013, 2020). "Expression was only observed in melanoma, where VCX2 protein was detected in 4/31 specimens." (PMID 33634013, 2020). "Although this protein was found to be strictly limited to testes germ cells in normal tissues and therefore could be a suitable target for immunotherapy, staining of a high number of tumor specimens from different types of cancer showed that VCX2 is only expressed in a small number of melanomas." (PMID 33634013, 2020). "Next, we investigated if epigenetic priming could also induce VCX2 in melanoma cells." (PMID 33634013, 2020). "Epigenetic treatment of MZ2-MEL melanoma cells with guadecitabine and valproic acid did not produce any VCX2-positive cells." (PMID 33634013, 2020).
cancer (1 paper, 2020). A tumor composed of atypical neoplastic, often pleomorphic cells that invade other tissues. "To investigate the potential of VCX2 as a novel therapeutic target for immunotherapy, we analyzed its expression in normal tissues and different types of cancer using immunohistochemical staining." (PMID 33634013, 2020). "We aimed to further investigate the potential of VCX/Y as new targets for immunotherapy, focusing mainly on VCX2, by investigating VCX2 expression in normal and cancer tissues and examining the inducibility of VCX2 by epigenetic treatment." (PMID 33634013, 2020). "Our results show that the expression of VCX2 can be epigenetically induced in cancer cells and therefore could be an attractive target for immunotherapy of cancer." (PMID 33634013, 2020). "In this study, we characterized the expression of VCX2, a member of the VCX/Y cancer/testis antigen family, in a large panel of normal tissues and tumors from multiple cancer types using immunohistochemical staining and RNA expression data." (PMID 33634013, 2020). "We further compared the expression of VCX2 to that of other VCX/Y gene members among normal and cancer tissues." (PMID 33634013, 2020). "In this study, we have demonstrated that VCX2 and other VCX genes are amenable to epigenetic induction by DNA methyltransferase and HDAC inhibitors in cancer cell lines and tumors and therefore may represent new targets for cancer immunotherapy." (PMID 33634013, 2020).
tumor (1 paper, 2020). "The fact that VCX2 expression is restricted to testis, which is an immune-privileged organ, diminishes the risk of off-tumor toxicity when targeting VCX2 and increases the potential of VCX2 as a target for immunotherapy." (PMID 33634013, 2020). "No VCX2 expression was observed in vehicle-treated PDX tumors, but VCX2 expression was observed in a small number of cells (<5%) in the guadecitabine-treated PDX tumor." (PMID 33634013, 2020).
VCX2 also shares sentences with these, for which no sentence is quoted: focal epilepsy (1 paper); hepatocellular carcinoma (1); ichthyosis (1); lung carcinoma (1); metastatic melanoma (1).